BDNF (brain derived neurotrophic factor)
Diseases named in the same sentence as BDNF in open-access papers (continued):
Sharing a sentence is not in itself a finding about the gene and the disease.
depression (continued). "Depression not only leads to dysfunction of the BDNF system, but also accompanies a decrease in hippocampal neurogenesis, which can be reversed through antidepressant treatment." (PMID 40371339, 2025). "Preclinical studies suggest that flavonoids possess antidepressant properties by reversing depression-related deficits through their antioxidant activity, neurotransmitter modulation, increased BDNF levels, and regulation of key enzyme activities." (PMID 40551742, 2025). "Our findings revealed significant differential expression of genes such as Oprm1, BDNF, Tph2, and Zfp769 in the depression mouse model (p < 0.05)." (PMID 40656047, 2025). "Karege and colleagues found that individuals with depression exhibit significantly lower baseline serum BDNF levels, which increase in response to ketamine treatment." (PMID 40565369, 2025). "Aerobic protocols significantly elevate BDNF levels, improving depression-related neural network functionality." (PMID 40680227, 2025). "Structural MRI studies have demonstrated that BDNF-induced increases after antidepressant treatment will spare any structural consequences of depression, specifically the reduced structural volumes of the hippocampus." (PMID 40362507, 2025). "In Alzheimer’s disease (AD) models, PDE4 inhibitors improve cognitive function and alleviate depression-like behavior by activating the cAMP/CREB/BDNF pathway, promoting neuroprotection and reducing apoptosis." (PMID 39851514, 2025). "Park, Choi, and Lee similarly conducted a placebo-controlled flavonoid study using orange juice and observed improvements in depression alongside increased serum serotonin, BDNF, and reduced CRP—though the small sample again limits external validity." (PMID 40426956, 2025). "Some studies have found that an increased activity of brain-derived neurotrophic factor (BDNF) in the hippocampus plays a role in tonifying the kidney and brain, calming the mind, and relieving depression." (PMID 40429978, 2025). "In depression, altered chromatin accessibility have been observed at BDNF, GAD1, NR3C1 in response to stress." (PMID 41234420, 2025). "In the PREDIMED (Prevención con Dieta Mediterránea) study, in a subgroup analysis of participants with depression, participants randomized to a nut-supplemented Mediterranean diet had a higher level of plasma BDNF after 3 years than the control group." (PMID 39928205, 2025). "Ferroptosis is linked to depression by suppressing BDNF expression, while gut microorganisms influence BDNF and modulate depression through the brain-gut axis." (PMID 40066336, 2025). "Research indicates that acupuncture upregulates the expression of p-ERK1/2 and BDNF in the PFC in a depression rat model." (PMID 40018358, 2025). "Yoga and meditation not only reduce the severity of depression but also enhance the brain’s recovery capacity by increasing neuroplasticity markers such as BDNF." (PMID 39996878, 2025). "Lastly, BDNF and stress receptors have presented as potential targets for depression and anxiety, respectively." (PMID 39851502, 2025). "(2023) also found that after short‐term subcutaneous administration of irisin to healthy mice subjected to stressful situations, the BDNF mRNA level in the prefrontal cortex increased significantly, and the mice's depression‐like behaviors were mitigated." (PMID 40696815, 2025). "It is well-known that hippocampal BDNF regulates hippocampal neurogenesis and synaptic plasticity, and depression is accompanied with not only abnormal behaviors but also dysfunction in these two physiological processes." (PMID 40356991, 2025). "Meanwhile, the PI3K/Akt/mTOR signaling pathway, downstream of the BDNF/TrkB, is considered vital in the treatment of depression." (PMID 39796425, 2025). "Relatedly, BDNF promoter IV DNA methylation was significantly altered in HD patients, with specific methylation sites being inversely correlated with anxiety and depression scores, suggesting its role in psychiatric symptomatology." (PMID 40001897, 2025).
depression (continued). "As already stated, reduced levels of serum BDNF were described in patients with major depression, so much so that protective functions are attributed to BDNF in relation to the pathogenesis of depressive disorders." (PMID 39928205, 2025). "Clinical studies have shown that there is consistently around a 25–30% increase in plasma BDNF levels in individuals responding to SSRIs/SNRIs treatments, and this increase in plasma BDNF levels is correlated with symptom remission of depression." (PMID 40362507, 2025). "Tremella fuciformis alleviates chronic restraint stress-induced anxiety, depression, weight loss, and CORT dysregulation, while also improving neuroprotection by upregulating brain-derived neurotrophic factor expression and preserving hippocampal integrity." (PMID 40077789, 2025). "Although the role of BDNF in depression has been extensively studied in the hippocampus, only recently the activation of BDNF–TrkB pathway in the ventromedial PFC and NAc has been associated with treatments that rescue emotional deficits." (PMID 39754520, 2025). "Postmortem studies also reported decreased BDNF mRNA and protein levels, along with reduced Trkβ expression in the brain of patients with depression and suicide victims." (PMID 41155366, 2025). "Electrical stimulation can upregulate BDNF expression, thereby improving cognitive function in patients with depression." (PMID 41356690, 2025). "Our study is the first to reveal that the relationship between serum BDNF and chronic pain is distinctly modulated by sex and depression." (PMID 40222813, 2025). "ERK and BDNF-TrkB pathway activation interferes with three mechanisms that are central to depression’s pathophysiology: neuroinflammation, BDNF downregulation, and HPA axis overactivation." (PMID 41375608, 2025). "In summary, BDNF plays multiple roles in the pathogenesis of depression, including influencing neurogenesis, synaptic plasticity, neuroprotection, emotional regulation, and the ability to cope with stress." (PMID 40863989, 2025). "In summary, the results suggest that the POBTE intervention had a significant positive impact on improving certain variables such as BDNF, anxiety, depression, sleep quality, and physical activity compared to the control group." (PMID 41333068, 2025). "The downregulation of BDNF-CREB signaling in the hippocampus is considered a major factor in triggering depression." (PMID 40371339, 2025). "In this study, we explored the relationship between HDRS scores, serum BDNF, and IL-1β levels in individuals with depression from the southern part of India." (PMID 40904969, 2025). "VEGF crosses the blood–brain barrier, promotes hippocampal neurogenesis and acts synergistically with BDNF, making it a plausible biomarker for “growth-factor-responsive” depression." (PMID 41373485, 2025). "Chronic pain is often accompanied by mood disorders such as anxiety and depression, conditions in which BDNF levels are typically found to be reduced." (PMID 40066312, 2025). "While serum BDNF is a promising biomarker for CP, its reliability for gauging pain severity depends on patient sex and depression status." (PMID 40222813, 2025). "Indeed, stress and depression have been associated with epigenetic alterations in the genes involved in mediating resilience and vulnerability to stress, including stress response-related genes, neurotransmission and the expression of BDNF, one of the key mediators of neuroplasticity." (PMID 39846545, 2025). "These systems are also the key modulators of BDNF expression; monoamine–BDNF interaction is involved in the pathophysiology and treatment of depression, anxiety, and cognitive disorders." (PMID 41305643, 2025). "Dysfunction in the BDNF/TrkB signaling pathway reduces tyrosine phosphorylation of TrkB receptors in the brain, diminishing BDNF activity and resulting in depression-like symptoms." (PMID 40003622, 2025).
depression (continued). "Recent investigations suggest that the Nrf2/BDNF axis facilitates functional recovery in post‐stroke depression models." (PMID 41345421, 2025). "Since BDNF plays a pivotal role in antidepressant effects observed in animal models, BDNF mimetics, which stimulate TrkB receptor, are promising candidates to treat depression." (PMID 40005159, 2025). "Numerous studies have shown that BDNF alleviates depression symptoms through high-affinity binding to tropomyosin receptor kinase B (TrkB)." (PMID 40832603, 2025). "In CUMS mice models, EGCG improved depression behaviors by regulating the BDNF/TrkB signaling pathway, reducing apoptosis, and protecting hippocampal neurons." (PMID 39861389, 2025). "This is the first report on PN regulating the apelin signaling pathway in a depression-like mouse model, which in turn alleviates neuroinflammation, enhances BDNF production, and improves the production of neurotransmitters." (PMID 41268325, 2025). "Given the interconnection between pro-inflammatory cytokines, BDNF, and the severity of depression, these biomarkers are likely to influence the progression of the disorder." (PMID 40904969, 2025). "Elevated cortisol levels from HPA axis dysregulation further suppress BDNF, while gut microbiota imbalances commonly observed in depression also diminish BDNF activity." (PMID 41226736, 2025). "A further challenge lies in the fact that many proposed biomarkers of depression—such as BDNF, inflammatory cytokines, or markers of oxidative stress—exhibit substantial interindividual variability and low diagnostic specificity." (PMID 41516220, 2025). "Due to this, the present study aimed to examine the relationship between BDNF peripheral levels and depression and anxiety symptoms in people with CUD." (PMID 40943216, 2025). "Their potential to enhance the production of BDNF, an essential neurotransmitter for neuronal survival that is often reduced in individuals with depression." (PMID 41292566, 2025). "Clinical and preclinical studies have consistently shown that individuals with depression exhibit significantly reduced BDNF levels in the hippocampus, PFC, and peripheral blood, including plasma and serum." (PMID 40004867, 2025). "In male patients with depression, BDNF levels were observed to decrease initially after aerobic exercise and then increase again after 60 min of rest." (PMID 40933306, 2025). "Relationship between the number of stressful life events and serum BDNF and IL-1β levels in patients with depression." (PMID 40904969, 2025). "In recent five years, two most frontier potential areas in studying depression were gut microbiota dysbiosis and BDNF." (PMID 40520890, 2025). "Experimental studies have highlighted how sex differences in BDNF levels contribute to variations in pain perception and the development of pain‐induced mental disorders, such as depression and anxiety." (PMID 40222813, 2025). "Conversely, the depression symptoms would be alleviated with increased ERK phosphorylation in mouse hippocampi following the BDNF treatment." (PMID 39796425, 2025). "Compared to the non-depression group, the serum CaMKII, 5-HT, and BDNF levels were significantly lower in the depression group (P < .05)." (PMID 41366912, 2025). "The findings revealed a consistent upward trend in serum BDNF levels in adolescents with depression undergoing antidepressant treatment and interventions, mirroring the pattern observed for 5-HT." (PMID 41477617, 2025). "The present study investigates the role of biological markers, specifically serum BDNF and IL-1β levels, in patients with depression compared to healthy controls." (PMID 40904969, 2025). "Chronic METH use leads to decreased levels of BDNF in critical regions like the hippocampus and prefrontal cortex, which correlates with the onset of depression-like behaviors during withdrawal." (PMID 41042769, 2025).
depression (continued). "Some studies have reported positive correlations among exercise, BDNF, and symptom relief, particularly for depression." (PMID 40002745, 2025). "In the process of neurogenesis in depression, there are multiple regulatory signaling pathways, including the BDNF–TrkB signaling pathway." (PMID 40607033, 2025). "Inflammatory markers such as CRP and IL-6, as well as neurotrophins including BDNF, NGF, and VEGF, are closely associated with depression." (PMID 41589304, 2025). "ANOVA revealed a significant decrease in BDNF levels in the cortex (p = 0.034) and hippocampus (p = 0.036) of the reserpine-induced depression model." (PMID 40522360, 2025). "Similar changes in brain GABA, glutamate and BDNF have been found in patients with depression, and their reversal appears to play an important role in the improvement of depressed mood." (PMID 39107588, 2025). "Specifically, it is believed that a decreased BDNF/trkB-mediated cell support may result in reduced neurogenesis, neuronal atrophy and glial cell loss in critical brain areas, and these abnormal processes have been related to increased vulnerability to depression and schizophrenia symptoms." (PMID 40867109, 2025). "Schurgers and colleagues found that ECT significantly increased the concentration of molecules involved in the BDNF/TrkB signaling cascade, which negatively correlated with depression scores in TRD patients." (PMID 40565369, 2025). "The importance of BDNF and its implications for mental health have been studied, with reports of lower serum BDNF in patients with major depressive disorder." (PMID 40722728, 2025). "Individuals with both higher 25(OH)D and BDNF levels exhibited the lowest depression severity, whereas those with lower levels of both biomarkers had the highest PHQ-9 scores." (PMID 40871684, 2025). "Each increase in BDNF levels corresponds to a decrease of several points on depression scales, while cognitive improvement is smaller and occurs only after longer-term supplementation or combined supplementation." (PMID 40871684, 2025). "In a mouse model of psoriasis with depression/anxiety, fluoxetine ameliorated depression/anxiety, increased brain BDNF mRNA levels and improved psoriasis lesions." (PMID 39959848, 2025). "BDNF plays a central role in neuronal survival, neurogenesis, and synaptic plasticity—mechanisms that are commonly disrupted in major depressive disorders." (PMID 40566026, 2025). "Consistent with this, β‐phenylethylamine in rodents ameliorates depression‐like and other CNS deficits (e.g., decreased hippocampal brain‐derived neurotrophic factor and TrkB expression) evoked by corticosterone injections." (PMID 40476341, 2025). "Increased peripheral BDNF and lower serum cortisol was found after 3 months of yoga in patients with depression (N = 32)." (PMID 39896238, 2025). "TAK-653’s apparent regulation of IL-6, cortisol, and BDNF aligns with emerging paradigms of depression as a disorder of neuroimmune crosstalk." (PMID 40564108, 2025). "A recent study found that combined aerobic and resistance exercise (AERE) is more effective than resistance exercise (RE), yoga, and qigong in promoting the expression of BDNF and alleviating depression." (PMID 40699781, 2025). "These agents have unmatched potency for treatment-resistant depression, and both ketamine and BDNF restore prefrontal cortical BDNF to the same range, and stress induces similar over coupling of deranged neural network." (PMID 40362507, 2025). "This systematic review evaluated the effects of green tea and its bioactive compounds (L-theanine, EGCG, etc.)on mood disturbance, including depression, anxiety, stress, and sleep, as well as BDNF." (PMID 40722728, 2025). "Studies show that whereas lower phosphorylated GSK3β correlates with the severity of depression, greater CREB activity and decreased BDNF levels are linked to AD, particularly in the moderate to severe stages of dementia." (PMID 40149774, 2025).
depression (continued). "Further studies are needed to clarify the relationship between BDNF, cytokines, and depression and to explore the potential use of these biomarkers in the diagnosis and treatment of depression." (PMID 40821647, 2025). "Poor sleep quality raises stress levels, which suppresses BDNF secretion and increases vulnerability to depression." (PMID 39997339, 2025). "Reduced BDNF levels contribute to the neuronal atrophy and impaired synaptic plasticity observed in depression." (PMID 40725146, 2025). "Alterations in the concentration of neurotrophic factors (brain-derived neurotrophic factor [BDNF] being the most studied) during depression result in altered functional plasticity, neuronal atrophy, and reduced synaptic connectivity and function." (PMID 40838256, 2025). "Although BDNF is known to play a central role in depression, relatively few studies have explored its expression in AD patients with comorbid depressive symptoms." (PMID 40529210, 2025). "Reduced peripheral BDNF levels have been consistently reported in patients diagnosed with major depressive disorder, bipolar disorder, schizophrenia, obsessive compulsive disorder, generalized anxiety disorder, and panic disorder." (PMID 41303216, 2025). "The brain-derived neurotrophic factor (BDNF) has been shown to play a critical role in the pathogenesis of depression and anxiety." (PMID 41141866, 2025). "BDNF and exercise can reduce depression and improve cognition through BDNF epigenetic regulation, building resistance." (PMID 40792048, 2025). "They likely have fewer instances of depression than elderly or adult patients with depression, indicating that their decrease in BDNF and 5-HT levels would be less than in other age groups, resulting in higher baseline levels." (PMID 41477617, 2025). "Research indicates that exercise can alleviate depression through neurobiological mechanisms, including upregulating the expression of neurotrophic factors such as BDNF and reducing inflammatory signaling pathways." (PMID 40591458, 2025). "In stress-related depression models, reduced histone acetylation in the prefrontal cortex and hippocampus correlates with downregulated expression of BDNF and CREB, key mediators of neuroplasticity and mood stabilization." (PMID 41589304, 2025). "Lipopolysaccharide-induced inflammation gave rise to depression-like phenotype by altering BDNF-Tropomyosin receptor kinase B (TrkB) signaling in the prefrontal cortex, hippocampus, and nucleus accumbens." (PMID 40655156, 2025). "This reduction lowers neuronal excitability and suppresses BDNF secretion, potentially promoting the development of depression." (PMID 40001468, 2025). "Why do adolescents with depression exhibit higher baseline levels of 5-HT and BDNF compared to other age groups?" (PMID 41477617, 2025). "BDNF, which belongs to the neurotrophic factor protein family, is critically involved in depression." (PMID 39796425, 2025). "In this study, we utilized the concentrations of serotonin (5-HT) and brain-derived neurotrophic factor (BDNF) as indicators to investigate the mechanisms of depression." (PMID 41477617, 2025). "The role of BDNF in the pathophysiology of depression has been intensively investigated for the last 20 years." (PMID 39968087, 2025). "Acupuncture treatment has been shown to induce a wide range of physiological processes, include increased expression of brain-derived neurotrophic factor (BDNF), which plays a vital role in both diabetes and depression." (PMID 40658313, 2025). "Preliminary exploratory signals are consistent with potential modulation of neuroplasticity (BDNF) and selected psychosocial outcomes (anxiety, depression, sleep quality, physical activity), supporting the biological plausibility of this approach." (PMID 41333068, 2025). "Phytocompounds such as curcumin, resveratrol, and apigenin have been shown to elevate BDNF expression in preclinical models, countering the synaptic deficits commonly observed in depression." (PMID 40426956, 2025).